HSD11B2 (hydroxysteroid 11-beta dehydrogenase 2)
Diseases named in the same sentence as HSD11B2 in open-access papers (continued):
Sharing a sentence is not in itself a finding about the gene and the disease.
Obesity (7 papers, 2015 to 2025). Accumulation of substantial excess body fat. "In the kidney, despite decreased Hsd11b2, Nox4, and Fn1 expression with obesity, histological analysis revealed extensive glomerular damage, including swelling, increased cellularity, and narrowed Bowman’s space, suggesting significant renal pathology." (PMID 40362895, 2025). "For instance, smoking and obesity increase norepinephrine in the body, which suppresses HSD11B2 expression levels." (PMID 26593902, 2015). "Furthermore, HSD11B2 adipose-specific overexpression had a positive impact on the metabolic status of obesity-induced mice." (PMID 35737302, 2022). "The abundance of transcripts of HSD11B1, HSD11B2, PER1, and NR3C1 were unaffected by obesity or insulin." (PMID 33270115, 2021).
Hypokalemia (5 papers, 2015 to 2026). An abnormally decreased potassium concentration in the blood. "For example, loss of Hsd11b2 activity causes Na+ retention in principal cells of the collecting duct of the kidney, hypokalaemia, polydipsia, polyuria, volume contraction, and salt-sensitive hypertension." (PMID 34028587, 2021). "In this model, ZFN-induced knockout of the Hsd11b2 gene causes inappropriate activation of the MR, leading to salt-sensitive hypertension, suppression of renin secretion, and hypokalemia (see Glossary)." (PMID 27935823, 2016). "This suggests that treatment with MR inhibitors might reverse the adverse cardiovascular effects of SAME (which include hypokalemia, hypertension, proteinuria and end-organ damage), while promoting the beneficial metabolic effects of Hsd11b2 inactivation." (PMID 27935823, 2016).
preeclampsia (5 papers, 2014 to 2025). Preeclampsia is a hypertensive disorder of pregnancy that is characterized by new-onset hypertension with proteinuria presenting after 20 weeks of gestation, and depending on mild or severe forms may initially present with severe headache, visual disturbances, and hyperreflexia. "When the Hsd11b2 gene is overexpressed, it can cause placental dysfunction, especially in early-onset preeclampsia." (PMID 32140111, 2020). "Our mRNA expression data showed a tendency towards higher HSD11B2 mRNA levels in the serum of women with preeclampsia, whereas placental HSD11B2 mRNA expression (and activity) has been found to be reduced in women with preeclampsia." (PMID 39684415, 2024). "We identified CYP17A1, HSD17B3, SRD5A1, CYP19A1, CYP11B1, HSD11B1 and HSD11B2 as potentially affected enzymes in preeclampsia." (PMID 39684415, 2024). "Preeclampsia reduces placental expression and activity of 11β-hydroxysteroid dehydrogenase type 2 (HSD11B2), leading to an increase in fetal glucocordicoids." (PMID 25200528, 2014). "Our findings suggest that the methyaltion status of HSD11B2 promoter is a potentially accessible biomarker for preeclampsia." (PMID 25200528, 2014). "Placental expression and activity of HSD11B2 is reduced in preeclampsia with comparison to normal pregnancy." (PMID 25200528, 2014). "In this investigation, we revealed for the first time the reduced fetal methylation at CpG sites of HSD11B2 promoter in preeclampsia, implying the expression of HSD11B2 is likely to be increased." (PMID 25200528, 2014). "We finally found that methylation levels of HSD11B2 promoter were significantly lower in preeclampsia than normal pregnancy." (PMID 25200528, 2014). "The mean methylation levels at the HSD11B2 promoter were significantly different between normal pregnancy and preeclampsia (P = 0.007)." (PMID 25200528, 2014). "mRNA expressions of genes of enzymes with significantly decreased precursor-to-product ratios (i.e., CYP17A1, HSD17B3, CYP11B1 and HSD11B2) was similar in women with preeclampsia and controls, but the RNA levels of these genes were higher in women with preeclampsia." (PMID 39684415, 2024). "The positive relationship between HSD11B2 promoter methylation and infants born to preeclamptic women with the hypomethylated HSD11B2 may be a potential marker for preeclampsia." (PMID 25200528, 2014). "Preeclampsia reduced methylation level at fetal HSD11B2 promoter." (PMID 25200528, 2014). "A positive correlation existed between HSD11B2 promoter methylation and preeclampsia." (PMID 25200528, 2014). "Taken these observations together with our findings, it is implied that hypomethylation status at the promoter of HSD11B2 may not be among the mechanisms linking intrauterine exposure to maternal preeclampsia and high risk of metabolic diseases in adulthood." (PMID 25200528, 2014). "Unpublished data from our laboratory showed the expression of HSD11B2 in fetal kidney of X-induced preeclampsia model is decreased, whereas intrauterine growth restriction (IUGR) increased the methylation at CpG sites of HSD11B2 promoter in animal model." (PMID 25200528, 2014). "Renal gene expression of Hsd11b2, Sgk1, Scnn1a, Nox4, and Fn1 was not different between mice who had a normal pregnancy and mice who had a preeclampsia-like pregnancy at 5 or 10 weeks postpartum (respectively)." (PMID 40425613, 2025). "The methylation levels of HSD11B2 promoter were not significantly different between mild and severe preeclampsia (P > 0.05 for all)." (PMID 25200528, 2014). "Predominantly placenta-expressed genes, down-regulated in module M1, are regulators of fetal growth (CSH1, HSD11B2), metabolism (ESRRG), estrogen synthesis (HSD17B1), and immune functions (LGALS14), some of which were reported to be down-regulated in preeclampsia." (PMID 30135684, 2018). "However, the alteration in fetal HSD11B2 expression and activity has never been delineated yet in preeclampsia." (PMID 25200528, 2014).
preeclampsia (continued). "Interestingly, our present finding of a hypomethylation level at fetal HSD11B2 promoter in preeclampsia is not consistent with findings from other published studies in this area." (PMID 25200528, 2014).
breast carcinoma (4 papers, 2018 to 2024). "The Renca cell line, which expressed the highest levels of Hsd11b1 and Hsd11b2 compared to mouse melanoma, breast cancer, colon cancer and hepatoma cell lines, was selected as a syngeneic renal cancer model for in vivo studies." (PMID 38170044, 2024). "Knockdown of other upregulated ABC genes including PRR13, EGLN3, HSD11B2, and MATN3 also inhibited the proliferation of various breast cancer cell lines (data not shown)." (PMID 32539762, 2020).
colorectal cancer (4 papers, 2018 to 2023). A primary or metastatic malignant neoplasm that affects the colon or rectum. "Qi found Sanguisorba officinalis L. had an activating effect on the key target proteins corticosteroid 11-beta-dehydrogenase isozyme 2, the enzyme encoded by HSD11B2, which was markedly decreased in colorectal cancer tissues and was positively correlated with the overall survival time of patients." (PMID 34202548, 2021). "The actin-associated formin homology 2 domain containing protein 1 (FHOD1) gene is upregulated in melanomas and modifies proliferation and tumor growth, and the HSD11B2 plays a role in metastasis in colorectal cancer." (PMID 34178034, 2021). "Compared with HSD11B2 isoform, the role of HSD11B1 in tumor biology remains elusive although an increased HSD11B1 mRNA expression was reported in adrenal cortical neoplasms and colorectal cancers." (PMID 30388854, 2018).
essential hypertension (4 papers, 2014 to 2024). Hypertension that presents without an identifiable cause. "The roles of the mineralocorticoid receptor and the HSD11B2 enzyme in primary hypertension are increasingly being recognized." (PMID 39931437, 2024).
diabetes (3 papers, 2014 to 2024). "Whether decreased oxidative capacity is a cause or consequence of diabetes is unknown, but the link with HSD11B2 downregulation has to be strongly considered." (PMID 25133511, 2014). "Changes in GR signaling were compounded by increased expression of GR, and reduced expression of FKBP5 and HSD11B2 in diabetes." (PMID 36068241, 2022). "We observed significantly lower expression levels of each gene in visceral tissues of diabetic patients than in obese subjects without diabetes: p < 0.001 for GR, p < 0.0001 for H6PDH, p < 0.01 for HSD11B1, and p < 0.0001 for HSD11B2." (PMID 38791098, 2024).
intrauterine growth restriction (3 papers, 2012 to 2023). "In rats, intrauterine growth restriction is associated with both reduced HSD11B2 expression and increased HSD11B2 promoter methylation in kidneys at birth and these epigenetic effects lead to altered transcription factor binding of Sp1 and NF-κB." (PMID 22761903, 2012). "Reduced placental HSD11B2 mRNA levels have also been found associated with intrauterine growth retardation and pre-term birth, suggesting that the transcriptional activity of this enzyme may be predicted by maternal adversity and predictive of high risk birth outcomes." (PMID 22761903, 2012). "They demonstrated that HSD11b2 promoter methylation, a key component in the cortisol binding pathway, was significantly higher in neonates clinically diagnosed with intrauterine growth restriction (IUGR)." (PMID 30941337, 2019).
Hyperglycemia (2 papers, 2022 to 2023). An increased concentration of glucose in the blood. "The results from the current study additionally demonstrated that hyperglycemia is an important regulator of the expression of placental HSD11B2, an enzyme involved in the metabolism and inactivation of the glucocorticoid cortisol." (PMID 36930661, 2023). "BeWo cytotrophoblasts exposed to hyperglycemia displayed increased mRNA expression of ACSL1, HSD11B2, RPS6KA5, and LAP3 and reduced mRNA expression of CYP2F1, and HK2, concomitant with increased levels of: lactate, malonate, and riboflavin metabolites." (PMID 36930661, 2023).
magnesium deficiency (2 papers, 2012 to 2023). A nutritional condition produced by a deficiency of magnesium in the diet, characterized by anorexia, nausea, vomiting, lethargy, and weakness. "Increased hepatic HSD11B2 promoter methylation and decreased HSD11B2 mRNA has also been observed in neonatal offspring exposed to in utero magnesium deficiency." (PMID 22761903, 2012).
medulloblastoma (2 papers, 2019 to 2023). A malignant, invasive embryonal neoplasm arising from the cerebellum. "Importantly, genetic ablation of HSD11B2 reduced the size of medulloblastoma in the SmoM transgenic mouse model, suggesting that HSD11β2 inhibitors might be applied as cilia-related cancer therapies." (PMID 37006607, 2023).
adenoma (1 paper, 2023). A neoplasm arising from the epithelium. "HSD11B2 down-regulation in adenoma may promote its proliferation by promoting stemness and proinflammation." (PMID 36631756, 2023). "Overall, in the study, we systematically explored the differences in molecular expression profiles of colorectal mucosa and adenomas, elucidating enriched pathways, hub genes (CA2 and HSD11B2), disease prognosis and immune patterns." (PMID 36631756, 2023).
adrenal adenomas (1 paper, 2022). "HSD11B2 is not expressed in normal adrenals, but expressed in adrenal adenomas." (PMID 36561559, 2022).
asthma (1 paper, 2012). "One study found that in response to maternal asthma during pregnancy, there was no change in the activity of the male placental hydroxysteroid (11-beta) dehydrogenase 2 (HSD11B2) enzyme – the fetoplacental barrier to maternal cortisol, and the fetus continued to grow." (PMID 22792364, 2012).
chorioamnionitis (1 paper, 2018). A morphologic finding indicating inflammation of the fetal sac membranes. "Additionally, decreased expression of HSD11B2 in chorioamnionitis-associated placentas has been reported." (PMID 30373633, 2018).
chronic kidney disease (1 paper, 2025). Impairment of the renal function secondary to chronic kidney damage persisting for three or more months. "As the kidney is the major site of HSD11B2 expression, we hypothesized that patients with chronic kidney disease (CKD) would have reduced 11-oxygenated androgen biosynthesis due to impaired HSD11B2 activity." (PMID 39382395, 2025).
colitis (1 paper, 2019). Inflammation of the colon. "However, in a murine model of acute colitis we observed the opposite, where we found a significant upregulation of Hsd11b1 and a downregulation of Hsd11b2 upon colitis induction." (PMID 31316505, 2019).
congenital adrenal hyperplasia (1 paper, 2025). Congenital adrenal hyperplasia (CAH) is an inherited endocrine disorder caused by a steroidogenic enzyme deficiency that is characterized by adrenal insufficiency and variable degrees of hyper or hypo androgyny manifestations, depending of the type and the severity of the disease. "It should be noted, however, that the direct HSD11B2-mediated conversion of 11OHT to 11KT may play a larger role in congenital adrenal hyperplasia, where the adrenal output of 11OHT is significantly increased." (PMID 39382395, 2025).
corticotroph adenoma (1 paper, 2015). "Expression of both HSD11B1 and HSD11B2 have been documented in healthy dogs, and abnormal HSD11B1 and HSD11B2 expression patterns were found in canine corticotroph adenomas." (PMID 26262685, 2015).
endometrial tumors (1 paper, 2024). "We found that endometrial tumors of both low- and high-grade have significantly higher HSD11B2 levels than tumor-adjacent endometrium, which, like the control cell line HIEEC, displayed low HSD11B2/HSD11B1 ratio compared to EC of any grade." (PMID 39205690, 2024).
endometrioid tumor (1 paper, 2024). A benign, borderline, or malignant epithelial tumor of the female reproductive system characterized by the presence of glands and/or cysts lined by neoplastic cells that resemble endometrial cells. "Furthermore, HSD11B2 expression differed between grades and molecular subtypes, being most pronounced in low-grade endometrioid tumors and in MSI-high and NSMP molecular subtypes." (PMID 39205690, 2024).
leiomyoma (1 paper, 2025). A well-circumscribed benign smooth muscle neoplasm characterized by the presence of spindle cells with cigar-shaped nuclei, interlacing fascicles, and a whorled pattern. "In our leiomyoma cell culture RNA-seq data, HSD11B2 transcript levels were extremely low, representing less than 0.1 fragments per kilobase of transcript per million mapped reads and these levels remained extremely low after FKBP5-silencing." (PMID 40290045, 2025).
neuroendocrine disorder (1 paper, 2019). A disease or disorder that affects the neuroendocrine gland, any of the organized aggregations of cells that function as secretory or excretory organs and that release hormones in response to neural stimuli. "Hsd11b2 expression levels in the placenta has been shown to be dynamically regulated during cycles of acute and chronic stress, and its association with a long-term susceptibility of the offspring to neuroendocrine disorders is thought to be mediated by epigenetic mechanisms." (PMID 30718791, 2019).
oral cancer (1 paper, 2023). "Knockout of HSD11B2 promoted tumor angiogenesis (expression of EGFR and VEGFA), cell proliferation, and invasion in oral cancer cells." (PMID 36631756, 2023).
pituitary adenomas (1 paper, 2019). "Whilst the major glucocorticoid metabolising enzymes, 11β-hydroxysteroid dehydrogenase (11βHSD; HSD11B1 and HSD11B2), have been described in human pituitary adenomas, the activity of these enzymes within different pituitary cell types has not been reported." (PMID 31717753, 2019).
renal carcinoma (1 paper, 2024). A carcinoma arising from the epithelium of the renal parenchyma or the renal pelvis. "As HSD11B2 provides the substrates for HSD11B1 and higher levels of HSD11B2 activity have been described in the kidney compared to other tissues, we hypothesized that the inhibition of HSD11B1 could be more impactful in an orthotopic model of renal cancer." (PMID 38170044, 2024).
renal failure (1 paper, 2025). "Across each stage of CKD, this ratio demonstrated a stepwise increase indicative of an incremental loss of HSD11B2 activity and a reduction in downstream active 11-oxygenated androgens with progression of renal failure." (PMID 39382395, 2025).
sarcopenia (1 paper, 2025). Progressive decline in muscle mass due to aging which results in decreased functional capacity of muscles. "Conversely, we hypothesize that reduced HSD11B2 activity may contribute to reductions in lean muscle mass and sarcopenia in patients with CKD." (PMID 39382395, 2025).
tumor (12 papers, 2018 to 2026). "HSD11B2, as a critical enzyme, can convert cortisol to inactive cortisone and accelerate tumor progression and metastasis." (PMID 36631756, 2023). "The gene HSD11B2 regulated by progesterone, also known as hydroxysteroid (11-beta) dehydrogenase 2, has been frequently studied as a tumor promoter which promotes cancer progression by regulating interconversion of cortisol and cortisone." (PMID 32539762, 2020). "On the contrary, the other three downregulated genes including HMGCS2, HSD11B2, and OGDHL in higher immune score and stromal score groups indicated higher expressions of these genes were associated with more tumor purity and prognostic advantages." (PMID 31886185, 2019). "Several enzymes related to androgen biosynthesis and (re-)activation were highly expressed in all tumor biopsy samples, including HSD17B10, STS, SRD5A1, AKR1C3, and HSD11B2." (PMID 33974560, 2021). "We confirm substantial expression of HSD11B2 and AKR1C3 in nearly all CRPC tumor samples (93% and 100%, respectively)." (PMID 33974560, 2021). "It appears that the enzymes ChEH, HSD11B1 and HSD11B2 and CYP27A1 sit at a fulcrum balancing the formation from 5α,6-EC of the tumour suppressor DDA and from 5,6-EC, through 3β,5α,6β-triol, the oncometabolite 3β,5α-diHC-6O or the bile acid 3β,5α,6β-triHBA." (PMID 31009661, 2019). "Unlike NR3C2, HSD11B2 expression did not significantly change between GBM and normal tumor." (PMID 34769089, 2021).
cancer (5 papers, 2014 to 2023). A tumor composed of atypical neoplastic, often pleomorphic cells that invade other tissues. "The GSEA analysis suggested that HSD11B2 was related to multiple cancer-related genes and pathways, including cytosolic DNA-sensing pathway, JAK_STAT signaling pathway, T-cell receptor signaling pathway, and Toll-like receptor signaling pathway." (PMID 36313430, 2022). "All together, these data suggest that the downregulation of HSD11B2 expression in cancer colonic cell lines, after long-term insulin treatment would be the consequence of LIP overexpression, together with increased lactate production, both working at an epigenetic level." (PMID 25133511, 2014).
metabolic disease (2 papers, 2014 to 2023). A congenital disorder (due to inherited enzyme abnormality) or acquired (due to failure of a metabolically important organ) disorder resulting from an abnormal metabolic process. "Furthermore, the findings of this study suggest that targeting the miRNA-mediated regulation of Hsd11b2 mRNA expression could be a potential therapeutic strategy for preventing or treating metabolic disorders associated with DOHaD." (PMID 37432276, 2023). "However, further studies are required to address the mechanisms leading fetal hypomethylation at HSD11B2 promoter and the significance of the hypomethylation in the development of metabolic diseases." (PMID 25200528, 2014). "However, further studies are required to address the mechanisms of thehypomethylation at HSD11B2 promoter and the significance of the hypomethylation in the development of metabolic diseases of the fetals born to preeclamptic women." (PMID 25200528, 2014).
infection (1 paper, 2017). The state of being infected such as from the introduction of a foreign agent such as serum, vaccine, antigenic substance or organism. "Given that alterations in placental HSD11B2 expression are seen in pregnancies complicated with stress or infection, we next sought to determine if the biological mediators of stress (Cort) and infection (IL-1β) altered 11β-HSD2 protein expression at the cellular level." (PMID 28321257, 2017).